HGF (hepatocyte growth factor)
Diseases named in the same sentence as HGF in open-access papers (continued):
Sharing a sentence is not in itself a finding about the gene and the disease.
lung adenocarcinoma (continued). "Numerous reports indicate that growth factors, including TGF-β, epidermal growth factor (EGF), vascular endothelial growth factor, platelet-derived growth factor and hepatocyte growth factor can induce cancer cell EMT in a variety of cancers including lung adenocarcinoma." (PMID 24789104, 2014). "HGF expression can induce EGFR-TKI resistance to lung adenocarcinoma cells with EGFR-activating mutations, and MET inhibition can reduce proliferation of lung adenocarcinoma cell lines that show resistance to EGFR-TKIs." (PMID 22211244, 2012). "Therefore, HGF may act as a potential exogenous factor for inducing actin-rich TNTs in lung adenocarcinoma." (PMID 37550007, 2023). "Therefore, the aim of this study was to determine whether HGF/c-Met/β1-integrin signalling axis regulates TNT formation in A549 lung adenocarcinoma cells." (PMID 37550007, 2023). "Then, they examined the relationship between the PIWIL1 expression and mutations in lung adenocarcinoma, and eventually found that the PIWIL1 expression was remarkably higher in patients who did not have serine/threonine kinase 11 (STK11) or hepatocyte growth factor (HGF) mutations." (PMID 31890151, 2019). "Therefore, HGF–Met signalling might play important roles as a morphogen in some well‐differentiated types of lung adenocarcinoma." (PMID 26416301, 2015). "Furthermore, in addition to paracrine signalling of the c-Met receptor on NSCLC cells through HGF secretion by stromal fibroblasts, lung adenocarcinoma cells can also undergo autocrine signalling, raising the possibility that HGF could also play a role in TNT formation between cancer cells." (PMID 37550007, 2023). "The staining intensity of TNFSF14, JAM2, HGF, SPN, and LIFR in the tumors of 50 lung adenocarcinoma patients was first analyzed by immunohistochemistry and quantified according to H-scores." (PMID 36072807, 2022). "In lung adenocarcinoma cells, siRNA screen identified USP30 as one of the strongest hits involved in the hepatocyte growth factor (HGF)-induced cell scattering response, implying a role of USP30 in cancer cell metastatic." (PMID 35308234, 2022). "CM from CAFs increased the resistance of EGFR mutant lung adenocarcinoma cell line PC-9 cells to EGFR-TKI, indicating that the secretion of higher amounts of HGF is the robust feature of EGFR-TKI-resistance-promoting CAFs." (PMID 35326670, 2022). "The survival analysis shows that the prognosis of some tumors was significantly correlated with HGF/c-MET expression, including HNSC, lung adenocarcinoma (LUAD) and pancreatic adenocarcinoma (PAAD)." (PMID 34261467, 2021). "HGF/cMET signaling stimulates the expression and transcriptional activity of FOXM1 via its downstream pathways in pancreatic ductal adenocarcinoma and lung adenocarcinoma cells." (PMID 33806615, 2021). "In human bronchioloalveolar-subtype lung adenocarcinoma tissues, HGF and Met were detected in TANs and in cancer cells, respectively, suggesting that tumor progression can be provoked by TAN-derived HGF." (PMID 32422991, 2020). "For instance, the Hepatocyte growth factor (HGF)/c-mesenchymal-epithelial transition factor (c-Met), HGF/c-Met signaling pathway regulates the cirRNA CCDC66 expression to promote EMT and cisplatin resistance in lung adenocarcinoma cells." (PMID 37304411, 2022). "HGF is not spontaneously secreted at a detectable level in two gefitinib-sensitive lung adenocarcinoma cell lines (PC-9 and HCC827 cells)." (PMID 29455669, 2018). "Immunohistochemistry revealed that Met, a cognate receptor for HGF, was highly expressed and phosphorylated in neoplastic BECs from lung adenocarcinomas with well‐differentiated, not poorly differentiated, histogenesis." (PMID 26416301, 2015). "However, it is not known whether exogenous factors such as HGF can induce TNTs in lung adenocarcinoma cells." (PMID 37550007, 2023).
lung adenocarcinoma (continued). "It was reported that ROR1 repression inhibits the growth of lung adenocarcinoma regardless of EGFR status, and leads to multiple acquired resistance mechanisms, including EGFR T790M, MET amplification and hepatocyte growth factor (HGF) overexpression." (PMID 36497465, 2022).
liver disease (40 papers, 2007 to 2025). "Liver diseases are characterized by increased hepatocyte proliferation, which is associated with upregulation of cMet and/or HGF." (PMID 38935609, 2024). "We showed for the first time that a significant rise in plasma levels of HGF and Ang-2 at 3 and 7 days post 90Y-RE treatment was associated with progressive liver disease at 1-month follow-up." (PMID 28004357, 2016). "Previous work by our group demonstrates that in canine liver disease the primary molecular pathways associated with liver regeneration (e.g. the hepatocyte growth factor (HGF) signaling pathway) are highly comparable with those in rodents and humans." (PMID 24946932, 2014). "The HBV-HCC and HCV-HCC patient median plasma levels of AFP, AFU, and HGF were found to be significantly higher than those of the CH and LC patients, indicating that a high expression of these biomarkers was associated with the progression of liver disease." (PMID 33628599, 2021). "The hepatocyte growth factor (HGF)/c-Met pathway has been reported to play an important role in TGF-β-mediated liver disease progression." (PMID 38935609, 2024). "In this work, we utilized the Western diet (WD) mouse as a preclinical model to study alterations in HGF-induced signal transduction occurring in liver disease." (PMID 38216754, 2024). "K1K1 is highly stable and displays biological activities equivalent or superior to native HGF/SF in a variety of in vitro assay systems and in a mouse model of liver disease." (PMID 35905995, 2022). "When crossed with plasminogen‐deficient mice, which spontaneously develop liver disease induced by fibrin deposition, Plg double mutant mice exhibited significantly exacerbated liver disease, with reduced HGF production and hepatocyte proliferation." (PMID 33681672, 2021). "To test a broader clinical applicability of HGF/EGF mRNA-LNP to rescue liver diseases, we next evaluated the ability of HGF/EGF mRNA-LNP to accelerate liver regeneration in the well-established acetaminophen (APAP)-induced acute liver injury model." (PMID 33504774, 2021). "The serum level of HGF in liver diseases reflects liver injury and dysfunction, especially after partial hepatectomy (PH) in rats, and the protein level of HGF and activation of its receptor c‐Met in plasma increased immediately." (PMID 32492261, 2020). "Recombinant HGF protein has been shown to mitigate various liver disease models, such as alcohol-induced liver injury, hepatic ischemia-reperfusion injury, and fibrosis." (PMID 30083132, 2018). "In liver diseases, serum levels of HGF can increase due to enhanced production and decreased hepatic clearance, as the liver is the major organ through which HGF is eliminated from circulation." (PMID 26448742, 2015). "The serum levels of HGF are elevated in a variety of liver diseases, and HGF concentrations are used as a tumor marker for HCC." (PMID 26556861, 2015). "Plasma HGF concentrations are higher not only in liver diseases but also in patients with acute infections (positively correlating with inflammatory parameters, including C-reactive protein)." (PMID 26448742, 2015). "Those who reported a history of liver disease or malignancy on a baseline questionnaire were excluded, and plasma HGF was measured in the remaining 1470 participants, who were followed periodically for 10 years." (PMID 22672958, 2012). "The HGF is the most potent growth factor for hepatocytes and has been reported to be elevated in a number of liver diseases, including acute and chronic hepatitis, liver cirrhosis, HCC, primary biliary cirrhosis, and fulminant hepatic failure." (PMID 24281095, 2010). "Indeed, HGF can protect from liver injury, and the protective role of HGF occurs in healthy livers as well as in the early stage of liver disease." (PMID 40076928, 2025). "Engineered ASCs secreting HGF in response to IFN-β might be effective in fructose-mediated liver diseases by improving the intestinal barrier." (PMID 39126076, 2024).
liver disease (continued). "MSCs attenuate fibrosis by upregulating hepatocyte growth factor (HGF), insulin growth factor, and MSCs-derived EVs improve hepatocyte regeneration and modulate immune activity, demonstrating therapeutic benefits in various liver diseases." (PMID 35692794, 2022). "Moreover, plasma HGF strongly associated with Model for End-stage Liver Disease (MELD) score, a validated measure of liver disease severity, in HCC patients undergoing liver transplantation (Spearman rho = 0.54, p < 0.0001)." (PMID 30374460, 2018). "HGF, a potent mitogen for hepatocytes, is increased in various liver diseases." (PMID 27540507, 2016). "However, it is important to underline that the same molecules increased in CHC and LC patients with the sole exception of HGF that can be used for predicting the progression to HCC in patients with CHC-related liver disease and low albumin." (PMID 22745767, 2012). "In addition, they also found that HGF signaling plays a role in regulating the transcription profile of RPE.Thus, it will be intriguing to study whether altered expression of HGF in liver diseases could exsert distance influence on ocular condition." (PMID 35004861, 2021). "Since the amino acid sequence of feline HGF shows 97.5, 93.3, and 93.2% homology with those of canine, mouse, and human, the second aim of this study is that to examine whether feline-derived recombinant HGF can be used for the treatment of animals with liver diseases using a mouse model of NASH." (PMID 30083132, 2018). "Therefore, HGF is a potential therapeutic agent for treatment of fatal liver diseases." (PMID 21548996, 2011). "Previous researches have demonstrated that gut microbiota can modulate the release of IL-6, TNF-α, hepatocyte growth factor (HGF), IFN-γ and TGF-β, which are involved in liver regeneration and different liver disorders." (PMID 41333471, 2025). "Together, prolonged treatment with HGF + EGF mRNA-LNP leads to sustained and robust engraftment of functional PHHs, reduces the liver disease burden, and restores overall liver function in the clinically relevant p21/NSG-PiZ model." (PMID 38866762, 2024). "Disease annotations suggested three of the proteins are linked to different types of cancer (CDCP1, CCL3, ITGA11), whereas another two are related to liver diseases (CXCL10, HGF)." (PMID 36737481, 2023). "In this paper, we analyzed the clinical significance of serum angiogenic markers VEGF, Ang-1, Ang-2, angiopoietin receptor Tie1/2, HGF, and PECAM-1 in 62 patients with liver disease, out of which 33 were diagnosed with HCC and 29 with liver cirrhosis without signs of neoplasia." (PMID 35008171, 2021). "Serum levels of HGF did not significantly differ between CF patients with liver disease and those without." (PMID 23516586, 2013). "Among two cases of Legionella pneumonia with known liver diseases, one case was a non-survivor and HGF level was 9,584 pg/mL." (PMID 21429184, 2011). "Likewise, HGF plays a key role in liver regeneration, and there is growing evidence suggesting that CBD may offer therapeutic benefits in the context of liver disease." (PMID 41150065, 2025). "A number of these analytes were differentially expressed related to liver disease, including proteins with inflammatory and immunomodulatory activities, such as CCL15, pentraxin-3, TRAIL and MMP-3, among others, as well as the growth factors M-CSF, SCF, SCFG-β and HGF." (PMID 36230823, 2022). "Finally, in order to find the significance of HGF in cholesterol-relevant human liver disease, such as nonalcoholic steatohepatitis in humans, we assayed serum HGF levels in patients with NASH." (PMID 27143995, 2016). "Similarly to HGF, it might well be that these discrepancies are due to the multiple functions of PTX3 on the one hand and also the different etiologies of liver disease, i.e. non-focally distributed NASH compared to focally distributed CFLD, on the other hand." (PMID 23516586, 2013).
Stroke (37 papers, 2009 to 2026). Sudden impairment of blood flow to a part of the brain due to occlusion or rupture of an artery to the brain. "Circulating HGF is associated with the incidence of stroke, demonstrating HGF as a marker of endothelial damage." (PMID 36247468, 2022). "Collectively, although HGF interventions have shown both good and bad effects in basic research, increased circulating HGF levels were related to the risk factors of stroke and predicted an adverse prognosis of stroke." (PMID 34421795, 2021). "Second, while we specifically focused on HGF’s association with CeVD in CIND and AD, it is important to follow-up with similar association studies on vascular or post-stroke dementias in order to further evaluate the nature of HGF changes in response to CeVD, and hence its diagnostic utility." (PMID 29410622, 2018). "In our previous study, we identified a significant elevation of HGF concentrations in the plasma of patients with ischemic stroke, suggesting its potential as an independent predictor of adverse stroke prognosis." (PMID 38954749, 2024). "This study assessed the potential of programmed death‐ligand 1 (PD‐L1) and hepatocyte growth factor (HGF)‐engineered mesenchymal stem cell‐derived exosomes (EXO‐PD‐L1‐HGF) in enhancing neurological recovery post‐stroke." (PMID 39049677, 2024). "In patients with post-stroke fatigue, the markers hepatocyte growth factor (HGF), interleukin-8 (IL-8), and macrophage inflammatory protein-1 alpha (MIP-1a) were elevated compared to patients without fatigue." (PMID 36756348, 2022). "Elastic net regression was applied to screen variables associated with stroke outcome; binary multivariable logistic analysis was then used to explore the relationship between HGF level and stroke outcome." (PMID 34421795, 2021). "The implication of the MET/STAT3/Bcl-2 pathway in HGF protection from apoptotic neuronal death in stroke has been recently suggested in a rat model of transient middle cerebral artery occlusion (tMCAO)." (PMID 34179015, 2021). "Several studies have provided evidence that HGF is an independent predictor of coronary heart disease, heart failure, stroke and progression of atherosclerosis." (PMID 35047572, 2021). "HGF improves the neurological consequences of stroke by reducing the infarct volume of the ischemic brain and by preventing neuronal death through the reduction of apoptosis." (PMID 34179015, 2021). "The hydrogels encapsulating HGF or EPO also increased migration of neuroblasts into the stroke-injured region." (PMID 32411087, 2020). "The administration of DPSCs overexpressing HGF during the acute phase of stroke increased their neuroprotective effects by modulating inflammation and blood-brain barrier permeability, thereby promoting improvements in post-ischemia/reperfusion brain injury." (PMID 30151417, 2018). "In this study, we intravenously transplanted DPSCs overexpressing the HGF gene in rats during the acute phase of stroke to enhance the therapeutic effects of DPSCs in brain damage after ischemia/reperfusion (I/R) injury." (PMID 30151417, 2018). "More fundamental studies are needed to elucidate the optimal therapeutic window and any long-term effects of DPSC/HGF transplantation for the treatment of stroke." (PMID 30151417, 2018). "Previous studies demonstrated that the epicortical delivery of EPO and HGF enhance neurogenesis in the SVZ in mouse models of stroke." (PMID 23093979, 2012). "Hepatocyte growth factor (HGF)-containing microspheres increased the number of new neurons migrating from the SVZ towards the injured striatum in a stroke model in mouse." (PMID 23093979, 2012). "Moreover, due to its major neuroprotective actions, HGF-based preclinical therapeutic strategies have been investigated in experimental stroke models." (PMID 39684220, 2024).
Stroke (continued). "Since MSCs possess the hereditary expression of PD‐L1 and HGF, genetically engineering these cells to overexpress the two molecules might be a good strategy for rescuing the neuroglial tissue injured by stroke, to enhance treatment efficacy." (PMID 39049677, 2024). "Notably, further growth and trophic factors, namely TGF-β, bFGF, IGF-1, HGF, and HGF, released or regulated by MSCs, are also involved in post-stroke neurological recovery." (PMID 36425795, 2022). "Recently, serum HGF levels were shown to be associated with poor prognosis at 3 months independent of stroke severity, especially in patients with AIS without heparin pretreatment." (PMID 34421795, 2021). "Therefore, the prognostic value of HGF within 24 h after stroke with functional outcome (modified Rankin scale and death at 90 d) in patients with first-ever AIS with or without heparin/t-PA treatment requires validation." (PMID 34421795, 2021). "Another way to deliver HGF is the use of hydrogel carriers, which are useful in supporting neurogenesis and mitigate apoptosis and autophagy after stroke in mice models." (PMID 34179015, 2021). "One of these studies found that the risk of incident stroke was 17% greater with every standard deviation increase in circulating HGF independent of sociodemographic and CVD risk factors." (PMID 35047572, 2021). "This, together with the fact that HGF/c-met is also a chemoattractant for stroke-mobilized bone-marrow-derived stem cells, indicates that HGF could be a prime target for angiogenic therapy after stroke." (PMID 19292924, 2009). "Similarly, HGF, a key factor in neuroprotection and tissue repair, increased shortly after treatment and then declined, indicating its involvement in the initial stages of post-stroke recovery." (PMID 41583506, 2026). "However, current research on the role of HGF in sICH is insufficient, making it difficult to determine whether it retains its protective effects in this subtype of stroke." (PMID 39170073, 2024). "Interestingly, our study revealed a decrease in HGF levels three months after the acute stroke event, suggesting its involvement not only in the inflammatory response to stroke but also in reflecting the response to cerebral ischaemia itself during the acute phase." (PMID 38802464, 2024). "Furthermore, the dysregulation of HGF, TGF-α, and CCL2 in BALF and lung tissue after ischemia could play an important role in the molecular mechanisms underlying stroke-induced lung damage." (PMID 35897671, 2022). "Moreover, HGF gene transfer with viral vectors reduces pain and inflammation in a neuropathic model, promotes neurite extension, and increases synaptogenesis in a stroke model." (PMID 34179015, 2021). "Moreover, increased serum HGF levels indicated higher stroke risk in older adults without previous symptomatic cardiovascular disease." (PMID 34253757, 2021). "HGF is released in response to endothelial injury, and there is evidence that elevated levels of HGF are an independent predictor of coronary heart disease (CHD), stroke, progression of atherosclerosis, and also heart failure." (PMID 39860501, 2025). "Measuring 65 plasma cytokines and chemokines revealed that individuals with stroke due to LAA, CE, and SVO have a stronger inflammatory response than those with sCeAD, particularly for the analytes HGF, SDF-1α, IL-2R, CD30, TNF-RII, IL-16, MIF, APRIL, and SCF." (PMID 38802464, 2024). "Usually, the serum level of IGF-1 in patients with stroke-derived intracerebral hemorrhage during admission (hospitalization) is lower than healthy controls, while VEGF and hepatocyte growth factor (HGF) are higher." (PMID 28373915, 2017). "In the studies with animal models of stroke, an increase in the expression of BDNF, GDNF, HGF, EGF, FGF-2, and IGF-1, as rapidly as 12 h after the insult and lasting until 5 days after stroke, has been described." (PMID 26607630, 2016).